CASP9 (caspase 9)
Diseases named in the same sentence as CASP9 in open-access papers (continued):
Sharing a sentence is not in itself a finding about the gene and the disease.
tumor (continued). "Paclitaxel directly induces apoptosis of several types of tumor cells through a variety of mechanisms, such as phosphorylation of Bcl-2, activation of caspase-3 and caspase-9, and the mitogen-activated protein kinase signal transduction pathway." (PMID 26223974, 2015). "These cells were further treated with the cryoablated tumor extracts, together with the inhibitors of caspase-8, caspase-9, and P2X7 ATP receptor, respectively, for 12 h." (PMID 24818132, 2014). "Although caspase-9 and -10 are executors of apoptosis, little is known of their prognostic value in primary tumours." (PMID 25157404, 2014). "Quercetin facilitates apoptosis of tumour cells by caspase 3 and caspase 9 activation and cytochrome c release." (PMID 24366851, 2014). "It has been demonstrated in various tumour cell lines that sorafenib induced mitochondrial damage manifested by cytochrome c release into the cytosol, caspase 9 and 3 activation, and in consequence, apoptosis mediated through an intrinsic pathway." (PMID 24366851, 2014). "On the other hand, the TK/GCV system would induce downregulation of Bcl-2 and upregulation of caspase-9/-3 in the tumor cells, which increases the sensitivity to apoptosis induced by CTL." (PMID 25051201, 2014). "Bcl-XL suppresses the release of cytochrome c from the mitochondria, survivin interferes with caspase 9 activation in tumor cells and Bcl-XL, Mcl-1 and survivin can antagonize the proapoptotic effect of bax and Diablo in tumor cells." (PMID 24495648, 2014). "The mRNA levels of caspase-3, caspase-8, and caspase-9 of tumor tissues were reduced in different treatment groups compared with untreated group, particularly in combination group." (PMID 24307893, 2013). "MHCC97H cells with stable transfection of NET-1shRNA were injected subcutaneously to prepare nude mice model of HCC and Caspase-3, Caspase-8, and Caspase-9 mRNAs of tumor tissues in different groups were examined." (PMID 24307893, 2013). "In the in vivo study, ATL-I effectively suppressed tumor growth (A549) in transplanted tumor nude mice with up-regulation of caspase-3, caspase-9, and Bax and down-regulation of Bcl-2 and Bcl-XL." (PMID 24172243, 2013). "Activation of caspase-9 is a key factor in the mitochondrial apoptotic pathway driven by tumor suppressors." (PMID 24146957, 2013). "Cytochrome c promotes activation of caspase-9, which in turn promotes activation of caspase-3, leading to apoptosis of the tumor cell." (PMID 24223611, 2013). "To further investigate the mechanism about inhibiting tumor growth, we detected the mRNA levels of caspase-3, caspase-8, and caspase-9 of the tumor tissues from these four groups." (PMID 24307893, 2013). "In the apoptosis tumor cells, the staining of cytochrome C, caspase-9 and caspase-3 protein positive expression were mainly cytoplasm staining; a small part of the staining was nucleus and nuclear membrane staining and brownish yellow particles." (PMID 23347845, 2013). "In our study, we observed activated caspase 9 by western blot in TMTP1-DKK treated tumor cells, suggesting involvement of the mitochondrial pathway." (PMID 22984407, 2012). "Examination of tumor tissue from L-eEF-2K siRNA-treated mice revealed significant cleavage of caspase-9, a positive TUNEL assay (brown staining) and the down-regulation of the anti-apoptotic protein Bcl-2 (Figure." (PMID 22911754, 2012). "Further studies revealed that TCS-induced tumor cell apoptosis was attributed to activation of both caspase-8 and caspase-9 regulated pathways." (PMID 22957017, 2012).
tumor (continued). "It increases intracellular Cyt-C, activated caspase-9 and caspase-3 in a dose-dependent manner, therefore laminarin can be used as an effective drug for tumor prevention and treatment." (PMID 22907156, 2012). "The cleavage of caspase-3 and caspase-9 proteins was markedly higher in the tumor from the GSPs-treated mice than the control mice." (PMID 22087318, 2011). "Onconase (ONC), one member of bullfrog RNase A superfamily, displays apoptosis to tumor cells via caspase-9 dependent but caspase-8 independent pathway." (PMID 20089176, 2010). "Mechanistic studies indicate that decitabine induces caspase-8 and caspase-9 and sensitizes tumor cells to TRAIL, etoposide, cisplatin and paclitaxel." (PMID 21108789, 2010). "LA-treated tumor cells showed significantly enhanced cytochrome C release, and activities of caspase-9 and caspase-3." (PMID 20868498, 2010). "Presently, we investigate ways to increase the bystander cytotoxicity of cytochrome P450-based GDEPT by inhibiting the caspase 9-dependent apoptotic death that occurs in tumor cells infected with adenovirus expressing the CPA-activating P450 enzyme CYP2B6." (PMID 20836875, 2010). "In tumor cells, as well as 293 T cells, caspase-9 activity induced by Vpr or C81 was higher than caspase-8 activity." (PMID 19674438, 2009). "The results of the present study show that C81 and Vpr induce apoptosis via the activation of caspase-9 in tumor cells such as HeLa, HepG2, and 293 T cells." (PMID 19674438, 2009). "We noted that 24 h after CDDP application, the apoptotic rate of tumour cells decreased from 93±5 to 75±4% following inhibition of caspase-8, to 85±3% following inhibition of caspase-9, or to 49±6% following inhibition of caspase-3." (PMID 15266324, 2004). "In contrast to other tumour types, therefore, Akt seems to be of minor importance for inhibiting Bid cleavage and preventing caspase-9 activation in our RCC model system." (PMID 12771998, 2003). "Tumour sections obtained 3, 7 or 28 days after injection of effector cells were stained with anti-caspase-9 or -3 antibodies, specific for the cleaved and active caspase fragments only." (PMID 14647152, 2003). "Using RT–PCR, we found that caspase-9 and caspase-9S exhibited the same expression pattern, but that the expression in high stage tumours was slightly lower for both isoforms." (PMID 11870543, 2002). "CASP9 was strongly expressed in the ganglioneuroma, both tumours of stage 1, and both stage 4S tumours." (PMID 11870543, 2002). "Ten out of 14 stage 4 tumours showed CASP9 expression; four of them (case 126, 106, St129, and St130B) showed a strong expression, while the other three were very weak." (PMID 11870543, 2002). "Curcumin exerts the therapeutic effect mainly by inhibiting the nuclear factor-κB (NF-κB) signal pathway, inhibiting the production of cyclooxygenase-2 (COX-2), promoting the expression of caspase-9, and directly inducing reactive oxygen species (ROS) production in tumor cells." (PMID 38918994, 2025). "Notably, CASP9 was also highly expressed in macrophages, monocytes, and cycling cells, suggesting a broader role in the tumor microenvironment." (PMID 41201629, 2025). "In this study, we sought to integrate multi-omics data to investigate the potential significance of CASP9-driven apoptotic programs in malignant cell states and their interactions with the tumor immune microenvironment, and further developed a prognostic model with potential clinical relevance." (PMID 41201629, 2025). "First, the enrichment of CASP9-expressing tumor cells near macrophage-dense regions, together with the activation of the SPP1–CD44 axis, suggests that apoptosis-related programs may promote the recruitment and polarization of tumor-associated macrophages." (PMID 41201629, 2025).
tumor (continued). "Mechanistically, our findings raise several hypotheses regarding how CASP9-high malignant cells may influence tumor progression." (PMID 41201629, 2025). "Moreover, the five-gene signature derived from CASP9-stratified tumor cells shows promising prognostic value across independent cohorts." (PMID 41201629, 2025). "Tumor Inhibition: The expression of pro-apoptosis genes Bax, Cyt-C, Apaf-1, caspase-9, and caspase-3 was increased when comparing the Western blotting results to the negative control group, while the expression of anti-apoptosis genes Bcl-2 and Livin was decreased." (PMID 40297577, 2025). "CASP9 is closely related to the apoptosis process, with studies showing that it is frequently downregulated in PC cells, leading to chemotherapy resistance and promoting tumor survival." (PMID 40593037, 2025). "Furthermore, tissue-level protein blotting experiments verified that downregulation of BAG2 resulted in increased expression levels of cleaved caspase-3 and cleaved caspase-9 in tumor tissues." (PMID 40755756, 2025). "This activates caspase-3 and caspase-9, triggering apoptosis in tumor cells." (PMID 40507897, 2025). "Naif1 can significantly inhibit the growth rate of tumor cells and induce apoptosis through Casp9." (PMID 40507874, 2025). "To evaluate the biological effect of XL44 on tumor cells, we tested whether it induces cell death by immunoblotting for the apoptosis markers cleaved caspase-9 or cleaved caspase-3." (PMID 38509117, 2024). "Caspase-9 is an important caspase in tumour cell apoptosis signal transduction." (PMID 38495504, 2024). "The authors suggested that ROS generation of radiation could activate pyroptosis via GSDME/caspase-9/caspase-3 pathway in addition to apoptosis, which could further activate an anti-tumor immune response." (PMID 39398428, 2024). "Additionally, butyrate promotes the production of Caspase 9, leading to the apoptosis of tumor cells." (PMID 39355268, 2024). "Over-expression of BCL-XL or knock down of toxic BH3 domain proteins significantly reduced drug-induced tumor cell killing, however, expression of dominant negative caspase 9 was less protective than BCL-XL suggestive that both apoptotic and non-apoptotic cell killing was occurring." (PMID 38758815, 2024). "Furthermore, this study revealed that HG increased the levels of cleaved caspase-9 and caspase-3 to promote tumor cell apoptosis." (PMID 38962311, 2024). "Therefore, a rational approach for reducing on-target/off-tumor effects of anti-CD38 CAR-T cells using caspase-9-based suicide gene or affinity optimization has been developed and showed highly suitability for the generation of optimal CARs." (PMID 38783333, 2024). "The Polycladia crinita extract mediated its promising anticancerous action by enhancing apoptosis and mitigating inflammation via VEGF, Notch 1, NF-кB, IL-6, Cyclin D1, Caspase 9 and Caspase 3 expression/level, which manifested in promoting the total survival rate and the tumor volume decrease." (PMID 38469406, 2024). "In summary, our findings indicate that PRF treatment may potentially exert a tumor-suppressive effect by upregulating caspase 8 and caspase 9 gene expression, leading to the activation of both intrinsic and extrinsic apoptosis pathways." (PMID 39684700, 2024).
tumor (continued). "Mechanistic studies reveal that Fe-CDs can selectively promote tumor cell apoptosis through regulating PARP/Caspase 3/Caspase 9/BAX proteins, and activate antitumoral macrophages by inhibiting the IL-10/Arg-1 axis, which contributed to the superior anti-tumor performance of Fe-CDs." (PMID 37978538, 2023). "TCS significantly promoted the activation of Caspase 9, Caspase 8 and Caspase 3 in tumor tissues." (PMID 36674931, 2023). "Cyclophosphamide, doxorubicin, and vincristine, three of the main recipes in this program, were all shown to affect tumor cell death by stimulating apoptosis through cleavage of the caspase 3 and caspase 7 or caspase 9, which correlates with the mitochondrial pathway." (PMID 37160920, 2023). "We next investigated whether the simeprevir-inducible PRSIM_23 CID module incorporated into the Caspase 9-based kill switch could be used to regulate apoptosis in vivo, in the context of a tumor-bearing mouse model." (PMID 38012128, 2023). "Hederagenin increases apoptosis by suppressing the anti-apoptotic protein Bcl-2 in tumor cells, and it primarily stimulates the mitochondrial endogenous apoptosis pathway by activating polyadenosine diphosphate ribose polymerase, caspase-3, caspase-9, and Bax." (PMID 37120556, 2023). "Casp9 plays a central role in apoptosis and is a tumor suppressor, Fas is a death receptor involved in cascade of caspases that mediates apoptosis, while ubd encodes ubiquitin D which targets proteins for proteasome degradation and can mediate apoptosis in a caspase-dependent manner." (PMID 37836781, 2023). "On the other hand, ACHE and CASP9 have a protective effect against tumor progression." (PMID 36838660, 2023). "Prognostic PRGs, especially CASP9, which is the independent factor of ACC prognosis, may be closely correlated with immune-cell infiltration, tumor mutation burden, microsatellite instability, and immune checkpoints." (PMID 36911522, 2023). "Additionally, Western blot and RT-PCR analysis observed that supernatants and exo of M2 macrophages significantly inhibited the expression of apoptosis-related proteins (Caspase-3 and Caspase-9) in tumor cells." (PMID 37367063, 2023). "Moreover, IL-10 blockade enhanced the effect of the co-administration by eliciting higher levels of IFN-γ and caspase-9, reducing Il-10 secretion and provoking the regression of tumor size." (PMID 35752792, 2022). "Moreover, inhibiting caspase-9 can induce tumor cells to produce type I interferon, increase activity of tumor-specific CD8+T cells, delay tumor cell growth, and increase radiotherapy sensitivity." (PMID 35846123, 2022). "This study further analyzed the expression of caspase-9 and caspase-3 proteins in tumor tissue." (PMID 35269987, 2022). "Consistent with previous in vitro experiments, Ad-vp3 and Ad-vt treatment increased the levels of cleaved-PARP, cleaved-GSDME, cleaved-caspase-3, cleaved-caspase-9, and up-regulated the expression of bax and cytochrome C. In summary, apoptin can inhibit tumor growth and induce pyroptosis in vivo." (PMID 35002520, 2022). "STE029 could sensitize Gefitinib by inhibiting EGFR/PI3K/Akt pathway, blocking the tumor cell cycle and proliferation and inducing apoptosis through caspase-8 and caspase-9 dependent pathway." (PMID 36419390, 2022). "Since the most significant increase in the active caspase 3 level was observed after the treatment of HOS with compound 6, the next stage of the study was focused on determination of the active caspase 9 level in order to further explore the anti-tumor mechanisms of this compound against HOS cells." (PMID 35743158, 2022). "In addition, PELI1 knockdown significantly inhibited IR‐induced activation of apoptotic signaling pathways in TE‐1 and ECA‐109 tumor cells, which was reflected by the inhibition of the cleavage of caspase 9, caspase 7, caspase 3, and PARP." (PMID 34738714, 2022).
tumor (continued). "Moreover, concerning the mechanism through which IL-24 assists tumor clearance, a rise in caspase-9 and TRAIL levels was detected, which indicates the high involvement of the apoptotic pathway." (PMID 35752792, 2022). "In addition, RTP significantly increases the expression of cleaved caspase-9 and cleaved caspase-3 proteins in tumor tissues in mice." (PMID 35269987, 2022). "Cleaved Caspase 9 in treated tumor xenografts further confirms activation of apoptosis in tumor." (PMID 36078112, 2022). "Furthermore, we also observed activation of caspase 9, which indicates a role for apoptosis induction in tumor reduction." (PMID 35008323, 2021). "The combination of PC and topotecan to human prostate adenocarcinoma cells (LNCaP) increased the activity of caspase-9 and caspase-3, increased free radical oxygen (ROS) levels, induced apoptosis of tumor cells, and reduced side effects of topotecan in a rat tumor model." (PMID 33513794, 2021). "Furthermore, LPEPS oral administration induced tumor apoptosis by activating caspase cascade, including caspase-8, caspase-9, and caspase-3." (PMID 34945611, 2021). "Moreover, the treatment upregulated the concentration of apoptotic proteins (caspase 9) and increased infiltration of tumor microenvironment with CD11b + myeloid and Gr1 + MDSCs cells." (PMID 32370750, 2020). "Moreover, baicalein also has been proved to induce apoptosis by activating caspase-9/-3 and to inhibit tumor invasion and metastasis by reducing the expression of matrix metalloproteinase-2/-9 (MMP-2/-9)." (PMID 33276419, 2020). "The cIAP1 gene supports tumor growth by restraining apoptosis; this anti-apoptotic activity is achieved by inhibiting specific caspases, and the proteolysis of caspase-3 is prevented by inhibiting cytochrome c-induced activation of caspase-9." (PMID 32186702, 2020). "Additionally, after Mcl-1-specific SBO treatment for 3 d, Bak, activated caspase 9, and caspase 3 expression levels in the tumor tissues were markedly elevated in a dose-dependent manner." (PMID 33052877, 2020). "This suggests that caspase 9 suppresses tumor-intrinsic DNA sensing involving cGAS–STING." (PMID 33238631, 2020). "CASP9 is thought to play a central role in apoptosis and to be a tumor suppressor." (PMID 31681739, 2019). "Therefore, the anti-tumour mechanism of drug-drug combination is to induce apoptosis through up-regulating the activity of caspase-3 and caspase-9 by inhibiting the activity of bcl-2." (PMID 30872765, 2019). "After the sacrifice of the mice, the tumor xenografts were harvested and subjected to western blot analysis, which revealed an increased apoptotic response (Bax, cleaved-caspase-9 and cleaved-PARP) and the downregulation of proapoptotic proteins (Bcl-2), similar to the in vitro analysis results." (PMID 31739642, 2019). "In addition, the change of apoptotic markers caspase-3 and caspase-9 along with the results from the pathological assessment of necrosis further confirmed its positive regulatory effect on tumor pathogenesis in the molecular level." (PMID 31675995, 2019). "Furthermore, we have identified one of its direct and key targets—CASP9—which in turn, mediates tumor proliferation, migration, and invasion through cell apoptosis pathways, providing evidence in support of targeting miR-224/CASP9 in TNBC therapy." (PMID 30886656, 2019). "Furthermore, Glaucocalyxin A dose-dependently increased the ratio of Bax/Bcl-2 and the cleavage of caspase-3 and caspase-9 in tumor tissues." (PMID 29899333, 2018). "However, emetine had an opposite effect on the alternative splicing of Caspase 9 in different tumor cell lines." (PMID 29788973, 2018).